CYP3A4 (cytochrome P450 family 3 subfamily A member 4)
Diseases named in the same sentence as CYP3A4 in open-access papers (continued):
Sharing a sentence is not in itself a finding about the gene and the disease.
liver cancer (22 papers, 2007 to 2025). An epithelial or non-epithelial malignant neoplasm that arises from the liver. "The mechanism by which AFB1 causes liver cancer involves the oxidation of AFB1 in the liver by cytochrome P450 3A4 (CYP3A4) in microsomes; this process generates the reactive metabolite AFB1-8,9-epoxide (AFBO), which covalently binds to nucleic acids and leads to liver cancer." (PMID 39091297, 2024). "Regarding drug metabolism and hepatotoxicity, sorafenib, as a first-line targeted therapy for liver cancer, has its efficacy and toxicity heavily dependent on the metabolic activity of cytochrome P450 (CYP3A4)." (PMID 40308492, 2025). "The stage plot analysis further highlights the dynamic nature of these genes across different cancer stages, particularly in liver cancer, where CYP3A4, ESR1, and CYP19A1 showed significant changes." (PMID 39204124, 2024). "In liver cancer tissues, CYP3A4 was significantly downregulated, whereas AKR1C3 was significantly upregulated." (PMID 39204124, 2024). "CYP3A4, a P450 enzyme, has been confirmed to play a role in the occurrence and development of various tumors, for example in oxygen metabolism of liver cancer and progression of breast and prostate cancer." (PMID 36823159, 2023). "It is directly bound with PXR and inhibits PXR-mediated expression of CYP3A4 in human primary liver cancer cells." (PMID 35002522, 2022). "Another study investigated the hepatoprotective effects of bioactive compounds obtained from 50 Gentian species on aconitine-induced hepatotoxicity in the human liver cancer cell line HepG2 by analyzing molecular docking to the active sites of the human cytochrome P450 3A4 (CYP3A4) enzyme." (PMID 40871648, 2025). "Furthermore, luciferase assays in human liver cancer G2 (HepG2) cells confirmed that svRNAb regulates CYP3A4 expression by directly targeting CYP3A4 and interacting with a validated binding site in the CYP3A4 3′UTR." (PMID 37692527, 2024). "Alternatively, this could also be due to a PXR-mediated negative feedback loop attenuating the expression of SLC16A1, as it was demonstrated for the CYP3A4 target gene in HuH7 liver cancer cells overexpressing PXR." (PMID 34298852, 2021). "Further research is needed to elucidate whether PCN changes the expression and function of CYP3A4 in a rat model of liver cancer and whether it affects the pharmacokinetics and pharmacodynamics of sorafenib." (PMID 34721737, 2021). "In the group of liver cancer patients, the findings indicated that the expression levels of ESR1, SERPINE1, CYP2C9, and CYP3A4 were significantly reduced." (PMID 38905394, 2024). "Liver cancer patients with high expression of ESR1, CYP2C9, and CYP3A4 exhibited a greater overall survival curve compared to those with low expression." (PMID 38905394, 2024). "We examined the liver cancer stem cell or progenitor markers (AFP, CD133, EPCAM, and KRT19), and hepatocyte terminal differentiation markers (ALB, G6PC, CYP3A4, and HNF4A) in subgroup of patients with different SOX signature scores." (PMID 31462277, 2019). "CYP3A4 and CYP3A5 genotypes were determined in 574 individuals including 178 patients with primary liver cancer, 82 patients with gastric cancer, 151 patients with colorectal cancer, and 163 healthy individuals." (PMID 17605821, 2007). "Among them, typical liver cancer stem cell markers such as AFP and keratin 19 (KRT19) were upregulated in FOXM1-high HCC, whereas typical mature hepatocyte markers such as solute carrier organic anion transporter family member 1B1 (SLCO1B1) and cytochrome P450 3A4 (CYP3A4) were downregulated." (PMID 35955438, 2022).
colon carcinoma (21 papers, 2006 to 2025). "PXR promoter methylation is involved in the regulation of intestinal PXR and CYP3A4 mRNA expression and might be associated with the inter-individual variability of the drug responses of colon cancer cells." (PMID 21342487, 2011). "The miR-627 level was higher in gastric cancer, activated by calcitriol and suppressed CYP3A4 in colon cancer cells and was described to modulate TGF-β1-induced pulmonary fibrosis." (PMID 34827715, 2021). "Our results showed that PGRMC1 contributes to enhancement of the doxorubicin metabolism, which is mediated by CYP2D6 or CYP3A4 in human colon cancer HCT116 cells." (PMID 26988023, 2016). "Previous studies have suggested that PXR activation decreases drug sensitivity and augments chemoresistance in certain colon cancers mainly through the upregulation of CYP3A4 and multidrug resistance protein-1 (MDR1)." (PMID 24690092, 2014). "The 6 colon cancer cell lines were classified into two groups (high or low expression cells) based on the basal level of PXR/CYP3A4 mRNA." (PMID 21342487, 2011). "CYP3A4 is expressed in liver and colon and its overexpression seems particularly relevant in colon cancer, since it inactivates irinotecan and other xenobiotics, such as taxols and vinca alkaloids." (PMID 24212669, 2011). "Minor differences in the frequencies for individuals carrying the CYP3A4*1A plus CYP3A5*3 haplotypes were observed in some subgroups of gastric or colon cancer, as compared to healthy subjects, with p values under 0.05." (PMID 17605821, 2007). "It has been demonstrated that the activity of the CYP3A4 enzyme in CRC cells may affect the tumor’s receptivity to some colon cancer treatments." (PMID 37568755, 2023). "Epigenetic mechanisms are involved in the regulation of PXR/CYP3A4 pathways in colon cancer cells." (PMID 26703582, 2015). "We examined whether epigenetic mechanisms are involved in the regulation of PXR/CYP3A4 pathways in colon cancer cells." (PMID 21342487, 2011). "mRNA levels of PXR, CYP3A4 and vitamin D receptor (VDR) were evaluated by quantitative real-time PCR on 6 colon cancer cell lines (Caco-2, HT29, HCT116, SW48, LS180, and LoVo)." (PMID 21342487, 2011). "Furthermore, SN-38 was shown to activate PXR in human colon cancer cell lines LS180 and HCT116 and induce CYP3A4, CYP3A5, UGT1A1, and the ABC transporter MRP2." (PMID 35582377, 2021). "The effects of BCP obtained from curry leaf, a commonly used spice, on P-glycoprotein (P-gp) transport and CYP3A4 metabolism were evaluated in L-MDR1 (LLC-PK1 cells transfected with human MDR1 gene) and Caco-2 (human colon carcinoma) cells and CYP3A4 activity in pooled human liver microsomes." (PMID 32998300, 2020). "We hypothesized that PXR may play a key role in the colon cancer cell response to anticancer drugs by modulating expression of drug metabolizing enzymes and transporters including UGT1A, CYP3A4 and p-glycoprotein." (PMID 21342487, 2011). "In addition, an in vitro study of colon cancer stem cells demonstrated the contribution of CYP3A4 in the chemoresistance of colon cancer and its negative impact on disease-free survival in the patients." (PMID 35967794, 2022). "In the present study, 6 colon cancer cell lines showed heterogeneous mRNA expression profiles and were able to be classified into two groups with respect to their basal levels of the PXR/CYP3A4 transcripts (high expression cells, LS180 and LoVo; low expression cells Caco-2, HT29, HCT116, and SW48)." (PMID 21342487, 2011). "Furthermore, molecular docking results indicated the stable binding connections between TQ/5-FU and the hub targets, i.e., MAP2K2, CASP3, PIK3CA, ESR1, CYP3A4, CYP2C19, and CYP2C9, suggesting that TQ, in combination with 5-FU, may treat colon cancer by modulating these hub targets." (PMID 39334689, 2024).
colon carcinoma (continued). "In order to determine whether epigenetic mechanisms function in PXR and CYP3A4 regulation and intestinal metabolism, we examined DNA methylation and mRNA expression of several candidate genes on the PXR/CYP3A4 regulatory pathway in human colon cancer cell lines and tissues." (PMID 21342487, 2011). "Moreover, we show that LS180 colon cancer cells that overexpress SXR are less sensitive to CPT-11 treatment compared to control cells, indicating that this transcription factor is involved in drug resistance, probably through CYP3A4, CYP3A5, MDR1 and MRP1 upregulation." (PMID 21733184, 2011). "Notably, we observed that PXR controls the expression of genes that were previously reported to confer CSC chemoresistance or to have a negative impact on disease-free survival in colon cancer patients, including ABCG2, ABCC6, ALDH1A1, CYP3A4, or S100A10." (PMID 27448961, 2016).
chronic kidney disease (20 papers, 2009 to 2025). Impairment of the renal function secondary to chronic kidney damage persisting for three or more months. "Correspondingly no dose adjustments are recommended for patients with impaired kidney function implicating that changes of CYP3A4 expression in chronic kidney disease are of minor pharmacokinetic relevance for cyclosporine." (PMID 34054518, 2021). "It is known that expression of CYP3A4 can change in chronic kidney disease which mostly develops in the clinical course after kidney transplantation and was present in our clinical population too." (PMID 34054518, 2021). "On the other hand, advanced oxidation protein products that formed due to the ROS attack on proteins down-regulated the expression of CYP1A2 and CYP3A4 in the kidneys of rats’ models for chronic kidney disease." (PMID 34564652, 2021). "Of note fatalities during therapeutic use have been reported only in patients with chronic renal insufficiency taking unadjusted doses of colchicine or when colchicine has been given intravenously, or combined with CYP3A4 inhibitors." (PMID 32670263, 2020). "The expression of CYP1A2, CYP2C9, CYP2C19 and CYP3A4 was determined in leukocytes of 105 patients with end-stage renal disease and 110 healthy organ donors." (PMID 32638224, 2020). "The present study suggests that the decrease of 1,25-dihydroxyvitamin D and the accumulation of uremic toxins contributed to the decreased hepatic clearance of CYP3A4 substrates in patients with end-stage renal disease." (PMID 23965431, 2013). "Second, although direct evidence has previously been provided for the correlation between leukocyte expression and hepatic enzyme activities (as well as hepatic expression) of CYP1A2, CYP2C9, CYP2C19 and CYP3A4, it should be validated for patients with end-stage renal disease." (PMID 32638224, 2020). "Moreover, the expression of CYP3A4 is elevated in patients with end-stage renal disease." (PMID 27756246, 2016). "Poor CYP expression was expected in leukocytes of patients with end-stage renal disease; however, the expression of CYP1A2, CYP2C9, CYP2C19 and CYP3A4 was efficiently quantified using the refined method." (PMID 32638224, 2020). "For instance, the concentration of erythromycin, a substrate of cytochrome P450 3A4 (CYP3A4), has been reported to be elevated in patients with end-stage renal disease." (PMID 23965431, 2013). "Comparing organ donors and the patients with end-stage renal disease, significant differences were observed in the proportion of subjects expressed CYP mRNA at low, normal and high levels (Chi2 for CYP1A2: 40.2, for CYP2C9: 87.9, for CYP2C19: 47.2, for CYP3A4: 29.9; df = 2, p < 0.0001)." (PMID 32638224, 2020). "In patients with end-stage renal disease, erythromycin N-demethylation by CYP3A4 was also reported to decrease; however, the alteration of erythromycin clearance was not exclusively attributed to the reduced CYP3A4 activity, but also to the changes in transporter activities (OATPs, P-gp)." (PMID 32638224, 2020).
Cirrhosis (20 papers, 2007 to 2026). A chronic disorder of the liver in which liver tissue becomes scarred and is partially replaced by regenerative nodules and fibrotic tissue resulting in loss of liver function. "We hypothesized in this study that the decreased CYP3A activity in cirrhosis is associated with significantly upregulated miRNAs that regulate CYP3A4 gene expression by targeting nuclear receptors (PXR, CAR or PPARα) mRNA or directly targeting CYP3A4 mRNA." (PMID 24058572, 2013). "Based on these observations we speculate that cirrhosis is associated with increased expression of certain miRNAs which interfere with translation of CYP3A4 mRNA and synthesis of CYP3A protein." (PMID 24058572, 2013). "Also, the anatomical and pathophysiological changes associated with hepatic cirrhosis might contribute in the reduction of CYP3A4 metabolizing activity." (PMID 19690646, 2007). "Mavacamten, primarily metabolized by CYP2C19 and CYP3A4, poses challenges in patients with cirrhosis due to enzyme downregulation, which can significantly increase drug exposure." (PMID 41496082, 2026). "HCC cells with higher baseline CYP3A4 enzyme expression levels exhibited a cirrhosis-dependent increase in doxorubicin chemoresistance." (PMID 38429725, 2024). "HCC cells with higher expression levels of cytochrome p450-3A4 (CYP3A4) enzyme exhibited doxorubicin chemoresistance in a cirrhosis-dependent manner." (PMID 34948424, 2021). "● Cirrhosis and inflammation increased vascular damage, and permeability due to upregulated inflammatory cytokines. ● High CYP3A4 expressing HCC cells increased vascular damage and permeability." (PMID 32397454, 2020). "Compared with controls, the Km values of CYP1A2, CYP2A6, CYP2B6, CYP2C8, CYP2C19, CYP2E1, and CYP3A4/5 were higher in both in fibrosis and cirrhosis groups." (PMID 27203676, 2016). "A correlation of plasma levels of vitamin D metabolites and intestinal CYP3A4 activity showed only low levels of vitamin D metabolites in patients with cirrhosis as a result of the reduction of CYP3A protein expression." (PMID 26864540, 2016). "The expression of PXR, CYP3A4 and hsa-miR-148a in groups according to hsa-miR-148a level and cirrhosis status." (PMID 23527115, 2013). "The increase in the expression of nuclear receptors and CYP3A4 mRNA is suggestive of post-transcriptional regulation of hepatic CYP3A activity by miRNA in cirrhosis." (PMID 24058572, 2013). "Cirrhosis-induced physiological changes profoundly affect the pharmacokinetics of CYP2C19 and CYP3A4 substrate drugs, posing challenges to their clinical use." (PMID 41471097, 2025). "Background/Objectives: Cirrhosis significantly alters physiological function and drug metabolism, particularly for medications primarily metabolized by CYP2C19 and CYP3A4." (PMID 41471097, 2025). "Following validation of the developed PBPK model in healthy subjects, the model was applied to predict the pharmacokinetic profiles of CYP3A4 and CYP2C19 substrate drugs after intravenous or oral administration in 1000 virtual patients with cirrhosis." (PMID 41471097, 2025). "In general, we found that HCC cells with higher baseline levels of cytochrome p450-3A4 (CYP3A4) enzyme expression, HepG2 and C3Asub28, exhibited a cirrhosis-dependent increase in doxorubicin chemoresistance." (PMID 34262860, 2021). "In terms of Vmax, CYP2A6, CYP2B6, CYP2C9, CYP2D6, CYP2E1, and CYP3A4/5 were increased, while the Vmax values of CYP1A2 and CYP2C8 were decreased in both the cirrhosis and fibrosis groups compared to control subjects." (PMID 27203676, 2016). "Correlation analysis between miRNA and mRNA expression of CYP3A4 and select nuclear receptors (PXR, CAR and PPARα) in cirrhosis and normal liver tissue." (PMID 24058572, 2013). "The resistance of HuH-7 and Hep3B2 cells to doxorubicin was not altered in response to cirrhosis, whereas CYP3A4 expression of these cell lines did not change in response to cirrhosis." (PMID 34262860, 2021).
Cirrhosis (continued). "We also analyzed and found that mild cirrhosis status had no significant influence on PXR or CYP3A4 levels." (PMID 23527115, 2013). "Inhibition of P-gp, MRP2, and CYP3A4 might represent a valid option for decreasing intestinal first-pass effects on orally administered OCT, thereby increasing its bioavailability to alleviate PH in patients with cirrhosis." (PMID 33407159, 2021).
epilepsy (20 papers, 2011 to 2025). A brain disorder characterized by episodes of abnormally increased neuronal discharge resulting in transient episodes of sensory or motor neurological dysfunction, or psychic dysfunction. "In a study on pediatric patients with epilepsy, the single-nucleotide polymorphism (SNP) rs2242480 in CYP3A4 (previously known as the CYP3A4 *1G allele) was associated with drug responsiveness." (PMID 40918507, 2025). "Research conducted in 2013 demonstrated that there is a correlation between CYP3A4*1B polymorphism and the drug used in the treatment of epilepsy—carbamazepine." (PMID 31025537, 2019). "Being the patient also in therapy with carbamazepine 600 mg BID for epilepsy, the authors of the case report hypothesized that pulmonary embolism was caused by a decrease in serum rivaroxaban levels due to the enzymatic induction of CYP3A4 by carbamazepine." (PMID 30581412, 2018). "The anticonvulsant CBZ is widely prescribed in the long-term therapy of epilepsy and is a potent inducer of CYP3A4 and CYP2B6." (PMID 36559144, 2022). "Overall, abnormal elevation of CYP3A4 under epilepsy has pathological relevance to the mechanism of drug-resistance epilepsy." (PMID 33967789, 2021). "The allele CYP3A4*1G has been associated with lower serum levels of CBZ and CBZE in Chinese patients with epilepsy." (PMID 33217013, 2021). "Overexpression of CYP3A4 has been shown to correlate with that of MDR1 at the blood-brain barrier interface of patients with drug refractory epilepsy." (PMID 21569296, 2011). "Furthermore, CYP2B6 together with CYP3A4 are central to the metabolism of clobazam, a common anti-seizure medication used in the treatment of many forms of epilepsy." (PMID 33096940, 2020). "The authors supposed that the thrombotic event was due to the interaction between rivaroxaban and oxcarbazepine, which the patient was taking for epilepsy, and which, as a strong CYP3A4 inducer, could have reduced rivaroxaban efficacy." (PMID 30581412, 2018). "Most of CYP3A4 in brains are mainly distributed in neurons, which may be affected by epilepsy." (PMID 33967789, 2021). "The role of nuclear CYP3A4 and CYP2C9 in epilepsy relating to GRβ overexpression needs to be explored in the future." (PMID 35563330, 2022). "An experimental study showed an overexpression of CYP3A4, CYP2C9, and CYP2E1 in human brain microvascular endothelial cells of drug‐resistant patients with epilepsy while CYP2D6 and CYP2C19 were downregulated." (PMID 34560816, 2022). "Among the top ten hyper- and top ten hypo-methylated genes, a subset (i.e., GABRB1, LC34A2, CLCN6, CLCA4, CYP3A43, CYP3A4, CYP2C9) has been related to epilepsy in epidemiological, pathophysiological or clinical context (to be discussed further)." (PMID 28276448, 2017). "CYP3A4/A5 enzymes play a major role in the CBZ metabolism and in the onset of epilepsy pharmacoresistance." (PMID 26555147, 2015). "Thus, the initiation of carbamazepin, a drug known to have a large impact of CYP3A4 and often with a significant clinical impact if combined with other drugs whose metabolism being dependent of this enzyme, was studied in 8 paediatric patients with newly diagnosed epilepsy." (PMID 25835492, 2015). "Notably, increased CYP3A4 in BBB metabolizes some antiepileptics to neurotoxic metabolites, also worsening epilepsy." (PMID 33967789, 2021). "Data on brain specimens surgically resected from patients with epilepsy also showed that the protein level and activity of CYP3A4 in the brain region of epilepsy lesions were significantly increased compared to non-epileptic regions." (PMID 33967789, 2021). "Furthermore, CYP2B6 and CYP3A4, the human homologues of Cyp2b10 and Cyp3a11 (another CYP induced in this study), are central in the metabolism (N-demethylation) of clobazam, an anti-seizure medication used in the treatment of epilepsy." (PMID 31052254, 2019).